CYP3A5 (cytochrome P450 family 3 subfamily A member 5)
Diseases named in the same sentence as CYP3A5 in open-access papers (continued):
Sharing a sentence is not in itself a finding about the gene and the disease.
cancer (continued). "Among all the cancer cell lines examined, the PDAC cell line AsPC-1 had the highest expression of CYP3A5, while the normal pancreatic ductal epithelial cell line HPNE hardly expressed CYP3A5." (PMID 38560501, 2024). "A higher noroxycodone/oxycodone ratio and a higher daily oxycodone escalation rate was described in cancer patients carrying the CYP3A5*3/*3 genotype, however, an association of plasma concentrations and analgesic consumption to CYP3A5 genotype could not be confirmed in the present trial." (PMID 23555934, 2013). "In CYP3A5, the compelling correlation with regions North and South the Tropic of Cancer, makes it likely that it belongs to the yet not fully understood catalog of genetic adaptations triggered by environmental stresses." (PMID 26018448, 2015).
infection (8 papers, 2015 to 2024). The state of being infected such as from the introduction of a foreign agent such as serum, vaccine, antigenic substance or organism. "Baseline infection intensity and CYP3A5 genotype were significant predictors of treatment associated-adverse events." (PMID 34531744, 2021). "In this regard, cell lines of gut origin and Vero E6 cells displayed a trend showing opposite expression patterns of CYP3A4 and CYP3A5 upon infection." (PMID 35229634, 2022). "This was closely followed by the rs1039108105 (GC) genotype (p = 0.03) of CYP3A5, which also increased the odds of clearing infection with the presence of this SNP by 3.04 (95% CI: 1.08, 8.51)." (PMID 35754834, 2022). "As a higher level of TAC is a risk for nephrotoxicity, neurotoxicity, or infection and a lower level of TAC is directly linked to acute rejection, this model can aid meticulous maintenance of TAC exposure in both CYP3A5 expressers and non-expressers." (PMID 31409869, 2019). "Our study also demonstrated a correlation between the regulation of the CYP3A5 gene and time after infection, and there was more enhanced down-regulation with infection." (PMID 26247779, 2015). "According to the optimized infection condition, COS-1 homogenates were prepared, and the activity of expressed CYP3A4 was measured with luciferin-IPA as a substrate, which is converted to luciferin by CYP3A4 but shows minimal cross-reactivity with CYP3A5 and CYP3A7." (PMID 35295333, 2022). "Given their divergent response to the infection, we decided to use both Vero E6 and T84 cells as models for testing cobicistat and remdesivir, to obtain data on the efficacy of the drug combination and on its possible reliance on increased expression of either CYP3A4 or CYP3A5." (PMID 35229634, 2022).
myopathy (5 papers, 2016 to 2023). A disease of the muscle in which the muscle fibers do not function properly. "Most studies included in this meta-analysis investigated myopathy; the pooled estimate of the effects of CYP3A5*3 on myopathy was similar to the overall one, although it showed a marginally statistical significance." (PMID 34357144, 2021). "Subgroup analysis showed that CYP3A5*3 tended to increase the risk of statin-induced myopathy without statistical significance, possibly because of insufficient power due to the small sample size." (PMID 34357144, 2021).
peripheral neuropathy (3 papers, 2022 to 2025). A disorder affecting the peripheral nervous system. "For survivors of pediatric ALL, European American survivors had more vincristine‐induced peripheral neuropathy than African American survivors (p = 0.007) and more neurotoxicity‐related dose reductions (p < 0.0001), likely due to vincristine metabolism being impacted by CYP3A5 expression." (PMID 40913328, 2025). "However, our data suggest that CYP3A metaboliser phenotype (CYP3A4/CYP3A5) is not a risk factor with a large effect size for taxane-induced peripheral neuropathy." (PMID 37469869, 2023). "Patients with preB ALL who expressed CYP3A5 showed less vincristine-induced peripheral neuropathy (VIPN), generated more M1, and had lower metabolic rates than those who did not express CYP3A5." (PMID 35628334, 2022).
Kidney Disease (2 papers, 2011 to 2021). "CYP3A5 is the primary CYP3A subfamily enzyme expressed in the human kidney and its aberrant expression may contribute to a broad spectrum of renal disorders." (PMID 33633318, 2021).
bacterial infection (1 paper, 2022). "What is more, patients with donor CYP3A5-expressed (adjusted OR 2.04, CI 1.06-3.92, and P = 0.032) were likely to have bacterial infection after LT." (PMID 36349313, 2022).
cardiovascular diseases (1 paper, 2022). "Therefore, it can be concluded that the proposed molecules might be potential CYP3A5 molecules for therapeutic application in cardiovascular diseases subjected to in vitro/in vivo validations." (PMID 36012627, 2022). "Cytochrome P450 3A5 (CYP3A5) is one of the crucial CYP family members and has already proven to be an important drug target for cardiovascular diseases." (PMID 36012627, 2022).
neurological diseases (1 paper, 2025). "However, the role of CYP3A5 in neurological diseases has not yet been clearly reported, indicating a need for further exploration of its potential mechanisms in neurological diseases, providing new directions for TBI treatment." (PMID 40353060, 2025).
CYP3A5 also shares sentences with these, for which no sentence is quoted: kidney (3 papers); type 2 diabetes (3); acute tubular necrosis (2); atrial fibrillation (2); Resistant Hypertension (2); age-related macular degeneration (1); alcoholic liver diseases (1); allergic rhinitis (1); anemia (1); Anxiety (1); atherosclerosis (1); autoimmune hepatitis (1); behavioral disorders (1); benign prostatic hyperplasia (1); Cholestatic liver disease (1); chronic leukemia (1); co infection (1); complication (1); Coronary Artery Disease (1); cystic fibrosis (1); dyslipidemia (1); End Stage Liver Disease (1); end-stage renal disease (1); essential hypertension (1); fibrosis (1); Giardia infection (1); graft versus host disease (1); heart failure (1); heart transplant (1); Hepatitis (1).
A further 38 diseases each share a sentence with CYP3A5 in 1 paper.